JAG1 (jagged canonical Notch ligand 1)
Diseases named in the same sentence as JAG1 in open-access papers (continued):
Sharing a sentence is not in itself a finding about the gene and the disease.
Alagille syndrome (continued). "Among its physiological functions, it is worth noting that Jag1 gene knockout in mice causes severe vascular defects that are lethal in early embryogenesis, and that JAG1 mutations in human beings are responsible for Alagille syndrome, an inherited multi-organ developmental disorder." (PMID 25309874, 2014). "Alagille syndrome (mutant JAG1) is typified by multiple abnormalities, such as dysfunctional vertebral segmentation (hemivertebrae) and craniofacial abnormalities." (PMID 39923120, 2025). "This pathway is regulated by genes such as RIPPLY2, TBX6, and JAG1; mutations in these genes have been linked to KFS, congenital scoliosis, and Alagille syndrome." (PMID 40004644, 2025). "JAG1 protein, a ligand of the NOTCH receptor, is associated with defects of vertebrae segmentation in Alagille syndrome." (PMID 40004644, 2025). "We investigated the function of Jag1 in cochlear patterning and signaling using Jag1Ndr/Ndr mice, which are a model of Alagille syndrome." (PMID 39373109, 2024). "In this study, we used the Nodder mouse model of Alagille syndrome, to address how Jag1 insufficiency affects individual SC and HC subtypes at single cell resolution." (PMID 39373109, 2024). "Alagille syndrome (ALGS) is an autosomal dominant disease characterized by a multisystem involvement including bile duct paucity and cholestasis, caused by JAG1 or NOTCH2 mutations in most of the cases." (PMID 37099537, 2023). "Alagille syndrome, for example, is an autosomal dominant disorder that results from nutations in JAG1 and NOTCH2." (PMID 37781534, 2023). "Liver disease in NAIC overlaps with the hepatic component of Alagille syndrome (AGS; OMIM #118450), an autosomal dominant disease caused by mutations in the notch signaling effectors JAG1 or NOTCH2 or the transcription factor HNF1B." (PMID 36656901, 2023). "NOTCH2 is also a possible receptor given that it acts as the receptor for JAG1 in other systems that are affected in Alagille syndrome." (PMID 36400760, 2022). "Infants with JAG1 mutations can suffer CHD, tetralogy of Fallot, and the more general Alagille syndrome, all associated with PDA72." (PMID 34350653, 2022). "Mutations in the JAGGED1 (JAG1) ligand and more rarely in the NOTCH2 receptor cause the Alagille syndrome that affects multiple organs, including heart, liver, kidney, and craniofacial organs." (PMID 34830355, 2021). "Studies of Alagille syndrome, a genetic disorder which results in bile duct paucity, have shown that the Notch ligand JAG1 is necessary for bile duct formation." (PMID 30589410, 2018). "Haploinsuffi for the Notch ligand JAG1 results in an autosomal-dominant, multisystem disorder known as Alagille syndrome, which is characterized by a congenital cholangiopathy of variable severity." (PMID 29142904, 2017). "As already mentioned, JAG1 gene haploinsufficiency is responsible for Alagille syndrome, whose clinical manifestations are highly variable." (PMID 22550961, 2012). "In contrast, MMS typically predominantly manifests as a secondary vasculopathy within monogenic disease frameworks, where primary genetic defects (e.g., JAG1 in Alagille syndrome, NF1 in RASopathies) disrupt cerebrovascular homeostasis through pathway-specific mechanisms." (PMID 40508049, 2025). "Lastly, an unanswered question is how variants in RBPJ, which is the sole transcription factor downstream of all NOTCH receptors, cause an N1/DLL4 syndrome (AOS) but not an N2/JAG1 syndrome (Alagille syndrome)." (PMID 41055965, 2025). "Alagille syndrome (ALGS) is a multisystem disorder, most often caused by JAG1 variants." (PMID 41293383, 2025). "Alagille syndrome (ALGS) is a multisystem condition characterized by cholestasis and bile duct paucity on liver biopsy and variable involvement of the heart, skeleton, eyes, kidneys, and face and caused by pathogenic variants in the JAG1 or NOTCH2 gene." (PMID 37511516, 2023).
Alagille syndrome (continued). "However, many of the cases of HCC described in Alagille syndrome date back to before the discovery of the JAG1 gene in 1997, and genetic tests were available only in five patients." (PMID 35884482, 2022). "A mutation in JAGGED1 (JAG1), a human NOTCH signaling ligand, causes Alagille syndrome." (PMID 35229725, 2022). "In JAG1 pathogenic variants typical of Alagille syndrome, the absence of functional protein creates hepatic progenitor cells with an intermediate hepatobiliary phenotype, unable to differentiate into biliary cells, resulting in ductopenia and cholestasis." (PMID 35884482, 2022). "HCC were reported in patients with features of Alagille syndrome (and in some cases even without liver involvement), suggesting a correlation with mutations in JAG1-NOTCH2 genes and HBCs by interfering with Notch signalling." (PMID 35884482, 2022). "In conclusion, these findings underline the need for genetic screening of family members and the regular surveillance in patients with Alagille syndrome associated with JAG1/NOTCH2 variants, including subjects with or without mild liver involvement." (PMID 35884482, 2022). "According to the work by Hofmann and coworkers, Jag1 in mice, conditional deletion of Jag1 in SM22α-expressing cells of the developing portal vein mesenchyme was sufficient to recapitulate the hepatic defects of Alagille syndrome." (PMID 34677194, 2021). "Furthermore, mutations in JAG1 or NOTCH2 cause Alagille syndrome (AGS), which has defects in multiple organs including the heart valves, and mutations in JAG1 or NOTCH1 have also been identified for a subset of tetralogy of Fallot patients." (PMID 34239905, 2021). "Deletions in JAG1 are often linked to Alagille Syndrome; however, complete duplications have not been specifically identified as disease-causing." (PMID 32733715, 2020). "Alagille syndrome is an autosomal dominant multisystem disorder with variable phenotypic penetrance, caused by heterozygous mutations in JAG1 or NOTCH2, encoding for the components of the Notch signaling pathway." (PMID 31157196, 2019). "Although genetic tests for liver cholestatic diseases were performed with negative results for Alagille syndrome (JAG1 and NOTCH2), a de-novo missense mutation of HNF1β gene was detected." (PMID 30791938, 2019). "Combining our cohort of 86 novel JAG1 and three novel NOTCH2 variants with previously published data (totaling 713 variants), we present the most comprehensive pathogenic variant overview for Alagille syndrome." (PMID 31343788, 2019). "Alagille syndrome (ALGS) is an autosomal dominant disorder, with multisystem involvement, which usually occurs due to Notch signaling pathway defects, mostly due to JAG1 mutation (ALGS type 1), but rarely due to neurogenic locus notch homolog protein (NOTCH2) mutation (ALGS type 2)." (PMID 30828556, 2018). "Notch2 appears to interact with Jag1 in the pathogenesis of Alagille syndrome." (PMID 29142904, 2017). "None of our 5 patients with mutations in JAG1 presenting as biliary atresia in early infancy met the diagnostic criteria for Alagille syndrome at the critical time of hospitalisation for neonatal cholestasis." (PMID 26618708, 2015). "Our aim was to identify and characterize individuals carrying JAG1 mutations among 72 patients with biliary atresia and to confirm the diagnosis in 4 patients with suspected Alagille syndrome having intrahepatic cholestasis without biliary atresia." (PMID 26618708, 2015). "Confirmation of the clinical diagnosis of Alagille syndrome in patients without biliary atresia by finding mostly novel pathogenic mutations in JAG1 was not surprising." (PMID 26618708, 2015). "Alagille syndrome (ALGS; OMIM 118450) is an autosomal dominant disorder that results from defects in the Notch signaling pathway, typically via mutations in the gene encoding a ligand for Notch receptors, JAGGED1 (JAG1)." (PMID 26076142, 2015).
Alagille syndrome (continued). "Neither we in this study nor any other group to the best of our knowledge, observed a carrier of JAG1 mutation with biliary atresia and no clinical features of Alagille syndrome similar to the 11 carriers of missense mutations reported by the Kohsaka ́s group." (PMID 26618708, 2015). "For example, except for the common disease gene JAG1 between Tetralogy of Fallot and Alagille syndrome, the two diseases interact through 5 PPIs with a p value < < 0.01 in the network, including JAG1 – NOTCH1, JAG1 – NOTCH2, JAG1 – NOTCH3, DLL1 - NOTCH2 and DLL1 – NOTCH3." (PMID 25539592, 2014). "Of note, JAG1 mutations are not specific for Alagille syndrome; in a large kindred study, JAG1 mutations were associated with congenital right heart obstructive disease without other diagnostic criteria of Alagille syndrome." (PMID 22937766, 2012). "It is interesting to note that the skeletal, facial and vertebral abnormalities of the Alagille syndrome correlate with arterial calcification, suggesting that Jag1 and Notch2 may also play a role in osteoblast and bone development." (PMID 19936191, 2008). "While improved mutation detection protocols can now identify JAG1 mutations in approximately 94% of patients diagnosed with Alagille syndrome, there are still some Alagille syndrome patients in whom no JAG1 mutations can be identified." (PMID 18365007, 2008). "Alagille syndrome (ALGS) is a rare genetic disease with autosomal dominant transmission, mainly caused by pathogenic variants in two gene-encoding proteins involved in the Notch Signaling Pathway: Jagged Canonical Notch Ligand 1 (JAG1) and Notch Receptor 2 (NOTCH2)." (PMID 39202394, 2024). "Interestingly, mutations in JAG1 and NOTCH2, the human homologs of the main ligands and receptor in the zebrafish notochord, lead to vertebrae malformations in human Alagille Syndrome." (PMID 35658971, 2022). "Moreover, several genes that are transactivated by this complex are associated with other, related syndromes, such as Jagged1 (JAG1; Alagille syndrome), MYC proto-oncogene N (MYCN; Feingold syndrome) and glioma-associated oncogene family zinc finger 3 (GLI3; Pallister-Hall syndrome)." (PMID 36361852, 2022). "However, Alagille syndrome was ruled out after neither JAG1 nor NOTCH2 gene mutations were identified." (PMID 31414320, 2019). "There have been reports of families with distinct JAG1 variants and a spectrum of cardiac defects in which no individual met diagnostic criteria, suggesting a spectrum of disease associated with JAG1 mutations that exists both within and outside a formal diagnosis of Alagille syndrome." (PMID 41523698, 2026). "Alagille syndrome (ALGS) is an autosomal dominant, multisystemic disorder due to haploinsufficiency in either the JAG1 gene (ALGS type 1) or the NOTCH2 gene (ALGS type 2)." (PMID 37890331, 2023). "Duplication of JAG1, BTBD3, and FLRT3, or ASXL1 induces Alagille syndrome, neurological dysfunction or chromatin remodeling." (PMID 32684981, 2020). "In others, such as Alagille syndrome (deletion of 20p12; OMIM 118450) or Rubinstein-Taybi syndrome (deletion of 16p13.3; OMIM 180849), haploinsufficiencies of a single gene (Jagged1 (JAG1) or CREBBP, respectively) accounts for all the characteristic features." (PMID 21857958, 2011). "JAG1 is well known to be involved in Alagille syndrome (ALGS); however, none of our participants presented any of the ALGS signs." (PMID 36729644, 2023). "Could single-gene analysis for JAG1, NOTCH2 (Alagille syndrome), SERPINA 1(A1ATd), DCDC2 (isolated neonatal sclerosing cholangitis), and ABCB4 (PFIC3) still be used to exclude these intrahepatic diseases and avoid diagnostic errors in the first step of the investigation?" (PMID 36292464, 2022).
ovarian carcinoma (51 papers, 2009 to 2026). A malignant neoplasm originating from the surface ovarian epithelium. "In brain and ovarian cancer, JAG1 is strongly expressed in tumor-associated blood vessels, suggesting its involvement in angiogenesis." (PMID 38022677, 2023). "It has been evidenced that acquired chemo-resistance in ovarian cancer is associated with the epigenetic silencing of microRNA-199b-5p via activation of JAG1-Notch1 signaling pathway." (PMID 28587194, 2017). "Taken together, our study suggests that the epigenetic silencing of miR-199b-5p during tumor progression is significantly associated with acquired chemoresistance in ovarian cancer through the activation of JAG1-Notch1 signaling." (PMID 24659709, 2014). "JAG1 has been reported to be strongly expressed by tumor-associated blood vessels, for example, in brain and ovarian cancer, where it can trigger Notch signaling in tumor cells (angiocrine function) to promote tumor growth." (PMID 25309874, 2014). "Therefore, this study suggests that the loss of miR-199b-5p increased the activation of JAG1-Notch1 signaling, which in turn promoted ovarian cancer progression and acquired chemoresistance." (PMID 24659709, 2014). "Moreover, western blot analysis revealed that the expression of JAG1 was upregulated and was inversely associated with the decreased expression level of miR-199b-5p in ovarian cancer cell lines such as C13*, SKOV3 and ES-2." (PMID 24659709, 2014). "Notch2/Notch3 and other NOTCH signaling molecules have achieved certain effects by inhibiting Jag1 in a mouse ovarian cancer model." (PMID 35332121, 2022). "Jag1/Notch axis participated in tumorigenesis and in promoting the progression of colorectal cancer, ovarian cancer, and cancer stem cell." (PMID 33329315, 2020). "Jagged-1 (Jag1) has been identified as the primary NOTCH3 ligand in ovarian carcinoma and Jag1/NOTCH3 interaction constitutes a juxtacrine loop promoting proliferation and dissemination of EOC cells within the intraperitoneal cavity." (PMID 33316986, 2020). "Knockdown of JAG1 by siRNA in several ovarian cancer cell lines decreased cell viability and reduced taxane resistance in one resistant cell line, SKOV3TRip2, in vitro." (PMID 29230082, 2017). "Here, we report that the loss of miR-199b-5p due to progressive epigenetic silencing leads to the activation of the JAG1-mediated Notch1 signaling cascade, thereby leading to the development of acquired chemoresistance in ovarian cancer." (PMID 24659709, 2014). "To study the function of JAG1 in ovarian cancer oncogenesis and chemoresistance, we evaluated the expression of JAG1 on a panel of ovarian cancer cell lines." (PMID 24659709, 2014). "In this study, we identified that the loss of miR-199b-5p, mediated by increased DNA methylation, is associated with acquired cisplatin resistance via aberrant activation of JAG1-Notch1 signaling in ovarian cancer." (PMID 24659709, 2014). "JAG1 activates primarily Notch3 in ovarian cancer and promotes proliferation and dissemination within the intraperitoneal cavity." (PMID 25309874, 2014). "A JAG1 pro-angiogenic role has also been reported in ovarian cancer models, where it was proven that Jag1 stromal silencing drastically reduced tumor microvascular density and neoplastic growth." (PMID 25309874, 2014). "In this study, miR-199b-5p was identified as another novel miRNA regulating the expression of JAG1 in ovarian cancer." (PMID 24659709, 2014). "Enforced expression of miR-199b-5p significantly and dose dependently reduced the expression of JAG1 in HEK293 cells as well as in two chemoresistant ovarian cancer cell lines, C13* and SKOV3." (PMID 24659709, 2014). "On the other hand, as a direct target of miR-199b-5p in ovarian cancer cells, JAG1 depletion by siRNAs also resulted in cell growth retardation and sensitization to cisplatin-induced cytotoxicity." (PMID 24659709, 2014).
ovarian carcinoma (continued). "Intriguingly, higher JAG1 expression was exclusively observed in cisplatin–resistant ovarian cancer cell lines (C13*, SKOV3 and A2780cp) compared with their corresponding cisplatin-sensitive cell lines (OV2008 and A2780s)." (PMID 24659709, 2014). "JAG1 is the main Notch ligand expressed by ovarian cancer cells; it is also strongly expressed by peritoneal mesothelial cells and tumor-associated endothelial cells." (PMID 25309874, 2014). "Likewise, the targeting of Notch ligands looked quite appealing, since JAG1 knockdown sensitized ovarian cancer cells to docetaxel and it disrupted tumor angiogenesis in vivo at least in part by affecting the crosstalk with GLI2." (PMID 34680255, 2021). "Using in vivo xenograft ovarian cancer models, knockdown of JAG1 also reduced tumor size." (PMID 29230082, 2017). "miR-199b-5p may be downregulated by activation of the JAG1-Notch1 signaling pathways in ovarian cancer." (PMID 26043836, 2015). "The epigenetic silencing of miR-199b-5p may at least partly activate JAG1-Notch1 signaling activity and promote acquired chemoresistance in ovarian cancer." (PMID 24659709, 2014). "Western blot analysis demonstrated that JAG1 was upregulated in most ovarian cancer cell lines." (PMID 24659709, 2014). "Thus far, this is the first report, to our knowledge, that the miR-199b-5p-JAG1-Notch1 signaling pathway is a novel regulatory circuit for acquired chemoresistance in ovarian cancer." (PMID 24659709, 2014). "Notably, the reduced expression of miR-199b-5p was found to be inversely correlated with the increased expression of JAG1 using an ovarian cancer tissue array." (PMID 24659709, 2014). "In a study of Notch ligands, Jag1 was shown to be the most highly expressed ligand in both ovarian cancer cells and surrounding peritoneal mesothelial cells with interaction of Jag1 and Notch3 resulting in activation of the signaling cascade and promotion of cell proliferation and adhesion." (PMID 25366565, 2014). "Intriguingly, the enforced expression of miR-199b-5p profoundly reduced HES1 luciferase reporter activity in SKOV3 cells by 35%, indicating the JAG1-Notch1 signaling cascade could be suppressed by miR-199b-5p in ovarian cancer cells." (PMID 24659709, 2014). "A recent study has suggested that the modulation of tumor angiogenesis by blocking VEGF signaling could reduce the chemoresistance of ovarian cancer, suggesting that JAG1/NOTCH1/neovascularization confers ovarian cancer chemoresistance." (PMID 24659709, 2014). "In contrast, activating Notch1 signaling by JAG1 or repressing miR-199b-5p by anti-miR-199b-5p could induce the activity of JAG1-Notch1 signaling in ovarian cancer cells." (PMID 24659709, 2014). "Hence, we speculated that JAG1-mediated Notch1 signaling activity is involved in ovarian cancer oncogenesis and chemoresistance." (PMID 24659709, 2014). "Thus, targeting JAG1 on both stroma and tumor cells could induce synergistic effects as demonstrated in an ovarian cancer model." (PMID 25309874, 2014). "Therefore, targeting the miR-199b-5p-JAG1-Notch1 regulatory circuit might be a therapeutic approach in cisplatin-resistant ovarian cancer." (PMID 24659709, 2014). "It was also suggested that in ovarian cancer, GATA1-regulated JAG1 plays a key regulatory role in cancer cell proliferation and metastasis." (PMID 39684309, 2024). "Dysregulation of the JAG1-Notch1 signaling cascade has been shown to activate a wide range of oncogenes in the HES, HEY and MYC families, thereby leading to ovarian cancer progression and chemoresistance." (PMID 24659709, 2014). "A recent analysis of the cancer genome atlas (TCGA) ovarian cancer data, largely comprised of HGSOC samples, has shown a significant reduction in DLL1, JAG1, NOCTH4, and an increase in HES1, NOCTH1 and NOTCH3 expression in OC samples compared to normal tissues." (PMID 40002854, 2025).